CXCL5 (C-X-C motif chemokine ligand 5)
Diseases named in the same sentence as CXCL5 in open-access papers (continued):
Sharing a sentence is not in itself a finding about the gene and the disease.
breast carcinoma (continued). "Although CXCL8 is the most commonly studied ligand of CXCR2 in breast cancer, other CXCR2 receptor agonists, such as GRO-α, GRO-β, GRO-γ and CXCL5, are co-regulated with CXCL8." (PMID 31788042, 2019). "Increased CXCR2 and its ligands CXCL1, CXCL5, and CXCL7 were found in co-cultured MSCs and breast cancer, with this axis augmenting breast cancer cell migration." (PMID 31130595, 2019). "Notably, CXCL5 has been described as a predictive factor for resistance to sunitinib in metastatic renal cell carcinoma (mRCC) and lapatinib in HER2-positive breast cancer cells." (PMID 39624081, 2024). "Other CXCR2 ligands may play a more important role in breast cancer than CXCL1, for example, CXCL5/epithelial-cell-derived neutrophil activating factor 78 (ENA78) and CXCL8/interleukin-8 (IL-8), whose expression is increased in breast tumors." (PMID 37108425, 2023). "Furthermore, KT inhibits CXCL5 and CXCR2 expression, suppressing the secondary growth of breast cancer cells on the bone, brain, and lungs." (PMID 36674719, 2023). "Based on the results of our preclinical investigation, we further analyzed whether clinical correlations occur between the expression levels of resistin, CXCL5, and ERK phosphorylation in breast cancer patients by immunohistochemistry." (PMID 36104403, 2022). "Abnormal elevations of CXCL5 and/or CXCR2 proteins have been noted in as many as 14 distinct malignant tumor types, including but not limited to CRC,263, 264 nonsmall cell lung cancer, breast cancer, bladder cancer, nasopharyngeal carcinoma, and so on." (PMID 35702353, 2022). "Moreover, when monocytes were co-cultured with the breast cancer line T47D that carries the MUC1-ST glycoform, CXCL5 was secreted by the myeloid cells and was reduced when the T47D cells were treated with sialidase to remove the sialic acid." (PMID 33149188, 2020). "The UALCAN analysis showed that only CXCL12 had a lower expression level in basal-like (triple-negative) breast cancer compared with luminal-like breast cancer, while CXCL5, IDO1, MIF, PTGS2, and VEGFA all had increased expression levels in basal-like breast cancer." (PMID 31293831, 2019). "Additionally, high levels of CXCL1, CXCL3, CXCL5, CXCL6, CXCL7 and CXCL8 are observed in drug-resistant breast cancer cells, which diminishes the effectiveness of other medical interventions." (PMID 31788042, 2019). "CXCL-5, -8, -9, and -16 were increased in breast cancer and dense breast tissue compared with the corresponding normal tissues." (PMID 29387062, 2017). "One study showed that chemokine (C-X-C) ligand 5 (CXCL5) could activate Raf/MEK/ERK, MSK1, Elk-1, and Snail, while E-cadherin was down-regulated in breast cancer cell lines." (PMID 25122124, 2014). "As CXCL5 may have a crucial role in the tumor microenvironment for breast cancer cell growth and metastasis, we focused our following investigations on this chemokine to further characterize its involvement in R-ADSC-mediated breast cancer malignant behaviors." (PMID 36104403, 2022). "Furthermore, CXCL5 can recruit MDSCs to the tumor via CXCR2 and promote breast cancer progression." (PMID 34439836, 2021). "In addition, 24 primary breast cancers were double stained for CD68 and CXCL5." (PMID 33149188, 2020). "Of note, in mammary carcinomas that do not express the TGF‐β type II receptor, CXCL5 expression is increased, resulting in the recruitment of MDSCs." (PMID 28618162, 2017). "Of the eight cytokines that were differentially expressed between seroma fluid from breast cancer and non-cancer patients, three were specifically up-regulated in malignant seroma fluid (GRO, ENA-78/CXCL5 and TIMP-2)." (PMID 26361584, 2015).
breast carcinoma (continued). "We observed that decreased TGFBR2 expression in human breast cancer patients correlated with decreased CXCL1, but not with CXCL5 in HER2+, PR + and ER + tumors." (PMID 25280532, 2014). "However, IL1RN, IL6ST, CXCL3, CXCL5, and CXCL6 gene expression levels were non-significant concerning clinical survival of breast cancer patients according to the Cox proportional Hazard model." (PMID 39201290, 2024). "However, IL1RN, IL6ST, CXCL3, CXCL5, and CXCL6 gene expression levels were non-significant concerning clinical survival of breast cancer patients." (PMID 39201290, 2024). "Organotypic microfluidic assays have shown that breast cancer cells do not exhibit extravasation dynamics into the muscle microenvironment, but do so into bone, through the interplay of breast cancer cell receptor CXCR2 and the chemokine CXCL5 secreted by the bone." (PMID 39439549, 2024).
pancreatic cancer (59 papers, 2008 to 2025). "Upon overexpression of Col5a1 in Ccn1‐deficient pancreatic cancer cells, the expression of Cxcl1 and Cxcl5 were upregulated." (PMID 40287974, 2025). "At the transcript level, mRNA expression of Ccl2, Ccl7, Cxcl1, Cxcl3, and Csf2 was markedly downregulated in Ccn1‐deficient pancreatic tumors, whereas Cxcl5, Csf1, and Csf3 expression remained unchanged, and Ccl20 mRNA was elevated." (PMID 40287974, 2025). "The activation of DDR1 by collagen enhanced the CXCL5 expression in orthotopically injected MDA-PATC 148 pancreatic cancer cells, which induced tumor-associated neutrophil (TAN) accumulation and neutrophil extracellular trap (NET) formation." (PMID 38339310, 2024). "While stromal cells elaborated multiple CXCR2 ligands, CXCL5 was mainly produced by pancreatic cancer cells and its expression was linked with mutant KRAS status." (PMID 38339310, 2024). "Mechanisms of omeprazole-induced Cxcl5 mRNA expression and its association with pancreatic cancer risk should be investigated." (PMID 38884019, 2024). "The mechanism of omeprazole-induced Cxcl5 mRNA expression and its association with pancreatic cancer risk should be investigated." (PMID 38884019, 2024). "In patients with pancreatic cancer, lower mRNA expression of CXCL5, 8, 9, 10, 11, and 17 was significantly associated with longer OS (p < 0.05)." (PMID 34439306, 2021). "The K–M curves demonstrated that a low expression level of CXCL5 was associated with a better prognosis in pancreatic cancer." (PMID 34497764, 2021). "CXCL5 is overexpressed in pancreatic cancer, and it is associated with poor survival in hepatocellular carcinoma, pancreatic cancer, and late-stage gastric cancer." (PMID 32337262, 2020). "Our finding that long-lasting OZ treatment might enhance Cxcl5 mRNA expression supposes the possible importance of this mechanism for the omeprazole-related pancreatic cancer risk." (PMID 38884019, 2024). "The activation of necroptosis could also mediate the immune escape of cancer cells and the rise of metastasis through the attraction of tumour-associated macrophages, for instance, in pancreatic cancer cells by releasing CXCL5 (C-X-C motif chemokine 5)." (PMID 38200509, 2024). "However, chemokine CCL20 is upregulated in patients with pancreatic cancer and related to advanced T categories, and high expression of CXCL5 is associated with shorter OS in hepatocellular and cholangiocarcinoma." (PMID 37779898, 2023). "CXCL5, derived from pancreatic cancer cells, primes tumor associated neutrophil to form NETs." (PMID 34868992, 2021). "CXCL5 is overexpressed in gastric cancer, prostate cancer, endometrial cancer, squamous cell cancer, hepatocellular carcinoma and pancreatic cancer, and increased expression of CXCL5 is associated with advanced tumor stages, local invasion, neutrophil infiltration and metastatic potential." (PMID 29743818, 2018). "We also found that pancreatic cancer patients with higher expression of hypoxia and metabolism-related genes whose expression is well-correlated with CXCL5 generally have poorer prognosis." (PMID 40050422, 2025). "ENA-78/CXCL5 has been shown to promote pancreatic cancer cell growth, migration, and invasion, and to predict poor prognosis." (PMID 39989973, 2025). "A previous report demonstrated increased CXCL5 levels in males with pancreatic cancer, although the expression pattern within the tumors was not determined." (PMID 41392310, 2025). "Critically, knockdown significantly decreased the growth of xenograft tumors in vivo, suggesting CXCL5 expression by pancreatic cancer cells is necessary not only for metastasis, but also for optimal cell proliferation." (PMID 38339310, 2024). "CAFs increase the expression of PD-L1 in pancreatic cancer by secreting CXCL5 and CXCL12 via phosphatidylinositol-3-kinase/protein kinase B signaling pathway, thus promoting the formation of immunosuppressive microenvironment." (PMID 37064113, 2023).
pancreatic cancer (continued). "We found an association of increased expression of CXCL9, CXCL10, and CXCL10 with decreased survival in pancreatic cancer and CXCL5 in cholangiocarcinoma." (PMID 35740353, 2022). "Inhibition of CXCL5 with small interfering RNA and neutralizing antibodies reduced tumor growth in a mouse model of pancreatic cancer." (PMID 36324574, 2022). "The data showed that most of chemokines, such as CX3CL1, CXCL16, CXCL3, CXCL9, and CXCL5, were significantly high expressed in pancreatic tumor tissues compared to normal tissues." (PMID 35478937, 2022). "As CXCL5 is one of the most upregulated factors in a pancreatic cancer mouse model with collagen I knockout, the authors proposed that this ECM alteration stimulated SOX9 transcription activation in cancer cells." (PMID 35453676, 2022). "The results showed that CXCL5 expression in pancreatic cancer was higher than that in other tumours, whereas in pancreatic cancer, CXCL16 expression was the highest." (PMID 35468838, 2022). "Necroptosis of pancreatic cancer cells at the invasion front can promote migration and invasion by releasing CXCL5." (PMID 35468838, 2022). "In pancreatic cancer, CXCL5 is overexpressed in cancer tissues and is significantly associated with poorer tumor differentiation, advanced clinical stage and shorter patient survival." (PMID 33458757, 2021). "Taken together, we conclude that collagen stimulates pancreatic cancer cells to produce CXCL5 through a DDR1/PKCθ/SYK/NF-κB pathway, and as a result, CXCL5 induces TANs to form NETs and promote cancer cell invasion and metastasis." (PMID 34237033, 2021). "Recent studies indicated that CXCL5 is aberrantly expressed in >14 different types of cancer, including hepatocellular carcinoma, prostate cancer, pancreatic cancer, and gastric cancer." (PMID 33458757, 2021). "CXCL5 acts as an oncogene and enhances cell growth and metastasis in several tumors, including bladder cancer, pancreatic cancer, cervical cancer, and cutaneous melanoma." (PMID 34194499, 2021). "In pancreatic cancer patients, the survival time of patients with higher levels of expression of CXCL5, 8, 9, 10, 11, and 17 was remarkably shortened." (PMID 34439306, 2021). "GABRP has been reported to play an immunomodulatory role in pancreatic cancer in a neurotransmitter independent manner, promoting macrophage infiltration by inducing the expression of CXCL5 and CCL20, and thereby affecting tumor growth and metastasis." (PMID 34957220, 2021). "Another study found that in response to KRAS/MEK inhibition, NF-ĸB activation induces CXCL5 secretion in pancreatic cancer cells, which elevated CD11b+Ly6G+ neutrophil infiltration." (PMID 34439836, 2021). "To confirm this was a DDR1-mediated effect, we overexpressed DDR1 in an additional 5 human pancreatic cancer cell lines, which resulted in a significant increase of CXCL5 expression upon collagen activation." (PMID 34237033, 2021). "For instance, overexpression of CXCL5 in pancreatic cancer cells promoted TAN recruitment and correlated with worse prognosis through the CXCL5–CXCR2 axes." (PMID 34497764, 2021). "CXCL5 is reportedly involved in intrahepatic cholangiocarcinoma, lung cancer, prostate cancer, pancreatic cancer, endometrial carcinoma, and squamous cell carcinoma of the head and neck." (PMID 33955820, 2021). "To validate our findings, we analyzed the correlation between CXCL5 expression and infiltration of these immune cells in pancreatic cancer from data of TCGA and GTEx." (PMID 32201508, 2020). "The infiltration of M2 polarized macrophages (R=0.26, p=0.00046) and neutrophils (R=0.36, p=8.1× e-7) was correlated with the expression of CXCL5 in pancreatic cancer tissues." (PMID 32201508, 2020). "High levels of CXCL5 correlate with a poor prognosis in patients with pancreatic cancer, colorectal cancer and hepatocellular carcinoma." (PMID 28399860, 2017).
pancreatic cancer (continued). "For example, CXCL1 and CXCL5, secreted by pancreas cancer cells, can activate CXCR2 in fibroblasts to stimulate the production of connective tissue growth factor that, in turn, fuels tumor progression." (PMID 26327350, 2015). "For CXCL5, previous reports are more equivocal, showing up-regulation correlated to poor survival in colorectal and pancreatic cancer, whereas another study showed correlation with under-expression of CXCL5 and poor survival for colorectal cancer." (PMID 23144859, 2012). "In an obese mouse model of pancreatic cancer, depletion of tumor-derived C-X-C motif chemokine ligand 5 (CXCL5) enhances the efficacy of anti-programmed cell death protein 1 (PD-1) immunotherapy, which is mediated by the upregulation of CD8+ T cell tumor infiltration." (PMID 40863244, 2025). "Interestingly, pancreatic cancer cells also appear to upregulate CXCL5 in response to gemcitabine chemotherapy, similar to how CCL2 is upregulated in response to radiotherapy." (PMID 38339310, 2024). "Moreover, CXCL5 mediates pancreatic cancer angiogenesis in mouse model by activating multiple signaling pathways, including signal transducer and activator of transcription pathways and extracellular signal–regulated kinase pathways in human endothelial cells." (PMID 36324574, 2022). "Besides NSCLC, several previous studies showed that increased expression level of CXCL5 was an adverse prognosis biomarker in pancreatic cancer, hepatocellular carcinoma, and bladder cancer." (PMID 35150082, 2022). "For patients with pancreatic cancer, Cxcl5 expression may be a reliable prognostic biomarker." (PMID 38884019, 2024). "Furthermore, CXCL5 could directly induce endothelial cell proliferation and invasion in vitro and promote tumor angiogenesis in non-small cell lung carcinoma and pancreatic cancer." (PMID 29743818, 2018). "In pancreatic cancer, Macro_APOE activated CXCL1 and CXCL5 expression through LDL receptor and NF-κB signaling in tumor cells, thereby establishing immunosuppressive niches." (PMID 40963562, 2025). "Our findings indicate a variation in the expression of CXCL5 and CXCR2 between primary foci and metastases in pancreatic cancer." (PMID 38430267, 2024). "Necroptotic pancreatic cancer cells induce peri-necroptotic immune suppression and invasion through CXCL1, CXCL5 and SAP130-Mincle signalling." (PMID 38926796, 2024). "Pancreatic cancer cells secret of various cytokines (such as IL-10, TGF-B and IL-23) and chemokines (such as CXCL1-3, CXCL5, CXCL12, CCI2 and VEGF) to enhance the activation of stromal cells and the accumulation of immunosuppressive cells." (PMID 37064113, 2023). "CXCL5 then recruited and polarized MDSC into a pro-tumor type to enhance the growth of pancreatic cancer cells." (PMID 35453676, 2022). "Primary pancreatic cancer cells from Ptf1a-Cre; lox-stop-lox-KrasG12D/+; Tgfbr2lox/lox mice secrete CXCR2 ligands including CXCL1, CXCL2, and CXCL5." (PMID 35159011, 2022). "In pancreatic cancer, APOE involved the expression of Cxcl1 and Cxcl5, known immunosuppressive factors, leading to immunosuppression." (PMID 35216190, 2022). "Treatment with KC-conditioned media on CAFs induces secretion of CXCL1, CXCL5, and CXCL7 greater than treatment with conditioned media from KRAS wild-type pancreatic cancer cells." (PMID 35159011, 2022). "Knockdown of Vasohibin-2 (VASH2), an endothelium-derived angiogenesis inhibitor, in murine pancreatic cancer cells downregulates NF-ĸB signaling, which results in decreased infiltration of CD11b+ Ly6G+ G-MDSC mediated by low Cxcl2 and Cxcl5." (PMID 34439836, 2021). "The CXC ligand family (CXCL5, CXCL9, CXCL10, CXCL11, and CXCL17) plays a vital role in regulating pancreatic cancer progression." (PMID 33393862, 2021). "CXCL1, CXCL5, CCL2, and IL-8 were significantly induced by TRAIL in lung, colorectal and pancreatic cancer cell lines." (PMID 31010082, 2019).